APOB (apolipoprotein B)
Diseases named in the same sentence as APOB in open-access papers (continued):
Sharing a sentence is not in itself a finding about the gene and the disease.
Hypercholesterolemia (continued). "A previous study has shown that a high-fat and high-cholesterol Western diet (WD)-induced maternal hypercholesterolemia increases the male offspring risk for NAFLD and metabolic diseases, which is related to the decreased ApoB gene expression regulated by DNA hypermethylation." (PMID 36979950, 2023). "This approach examined whether there was a reverse causal relationship between urinary stones and circulating lipids (TG, LDL-C, HDL-C, APOA, APOB, and Pure hypercholesterolaemia) along with lipid-lowering drugs (HMGCR inhibitors and PCSK9 inhibitors)." (PMID 38107516, 2023). "In contrast, elevated serum levels of LDL-C, HDL-C, APOA, APOB, Pure hypercholesterolaemia, as well as the use of lipid-lowering drugs such as HMGCR inhibitors and PCSK9 inhibitors, did not exhibit statistically significant associations with either an increased or decreased risk of urinary stones." (PMID 38107516, 2023). "In patients with heterozygous familial hypercholesterolemia (heFH), apoB was decreased by 33%." (PMID 37908502, 2023). "Similarly, Mipomersen, an FDA-approved orphan drug for homozygous familial hypercholesterolemia, was developed as an antisense oligonucleotide inhibitor of APOB-100 synthesis to target and complement a specific mRNA sequence involved in coding APOB-100." (PMID 38067270, 2023). "Family-based studies identified specific mutations in APOB and PCSK9 as etiological factors contributing to development of familial hypercholesterolemia by either impeding the binding of LDL particles to the receptors, thus hindering the uptake, or by enhancing the catabolism of LDL receptors." (PMID 38049831, 2023). "NAFD could explain the hypercholesterolemia that we highlighted, that could be a consequence of hepatic insulin resistance leading to reduced synthesis of ApoB and thus VLDL." (PMID 36670955, 2022). "Therefore, natural products or medications that can stimulate the intestinal receptor responsible for increasing the flux of apoB-lipoprotein derived cholesterol have the potential to open new preventative targets for hypercholesterolemia." (PMID 34829135, 2021). "In our study, APOB and PCSK9 mutations were synonymous, benign, and patients with these variants probably did not have a monogenic disorder of lipid metabolism, but they had a polygenic form of hypercholesterolemia." (PMID 33807407, 2021). "Mipomersen is directed against ApoB to counteract homozygous familial hypercholesterolemia." (PMID 33937351, 2021). "This drug effectively reduces LDL cholesterol, total cholesterol, and plasma APOB levels, but it is only approved for patients with homozygous familial hypercholesterolemia, whose plasma cholesterol and TG levels are up to four times the normal levels resulting in premature cardiovascular disease." (PMID 32760060, 2020).
Hypercholesterolemia (continued). "2,320 small molecules were screened to identify compounds that could reduce the levels of apoB in hepatocytes derived from Familial Hypercholesterolemia iPSCs." (PMID 31803747, 2019). "Mipomersen is a 20 nucleotide-long antisense oligonucleotide targeting apolipoprotein B (ApoB) mRNA indicated in homozygous familial hypercholesterolemia (HoFH) exerting its action by binding to ApoB mRNA and inhibiting the subsequent synthesis of the protein through RNase H activation." (PMID 30090066, 2018). "APOB is the target of an approved FDA drug for treatment of familial hypercholesterolemia." (PMID 30510157, 2018). "A codominant genetic model revealed a 2.69 risk increase (CI: 1.57–4.61) for the DD genotype (P = 0.009) independent of age, sex, BMI, smoking, hypercholesterolemia, and ethnicity suggesting APOB rs11279109 as an indicator for the increased risk of CHD." (PMID 29362515, 2017). "EPA corrected RA-induced hypercholesterolemia may through inhibit the oxidation of apolipoprotein B (ApoB)-containing lipid particles and suppress cholesterol domain formation." (PMID 29312596, 2017). "Importantly, ApoB-ASO (Mipomersen) is an FDA-approved drug with established safety profiles for treating familiar hypercholesterolemia." (PMID 28839185, 2017). "Apolipoprotein B (ApoB)-ASO is an FDA approved drug for treating familial hypercholesterolemia." (PMID 28839185, 2017). "Moreover, 34% of the participants with apolipoprotein B levels greater than 100 mg/dl developed hypercholesterolemia within a 5-year period." (PMID 18377643, 2008).
Hypercholesterolemia (continued). "This condition is due to point mutations that disrupt the conformation of the LDL receptor-binding domain of APOB, leading to decreased affinity for the receptor, decreased clearance of VLDL/IDL/LDL particles, hypercholesterolemia, and therefore an increased risk of atherosclerotic disease." (PMID 17233885, 2007). "However, the presence of likely pathogenic APOB variants in non-CVD patients supports a milder clinical phenotype often observed in APOB-associated hypercholesterolemia, marked by lower LDL-C burden and fewer xanthomas." (PMID 41398288, 2025). "Further, gene variants, including apolipoprotein E (APOE) isoforms, and single-nucleotide polymorphisms in genes encoding the LDL-receptor (LDL-R), apolipoprotein B (apoB), and proprotein convertase subtilisin/kexin type 9 (PCSK9) may result in severe hypercholesterolemia and hypertriglyceridemia." (PMID 39796476, 2024). "Therefore, targeted gene sequencing analysis was performed using custom panels focusing on the exome regions of 21 lipid-associated genes, including ABCG5, ABCG8, and familial hypercholesterolemia-causing genes (LDL receptor, LDLRAP1, PCSK9, and apolipoprotein B)." (PMID 38338819, 2024). "Nonetheless, in another patient (who had been diagnosed with hypercholesterolemia at 23 years old, whose highest LDLc recorded level was 232 mg/dL, and who had both hypercholesteremia and a premature ASCVD family history), genetic testing only identified the rare variant APOB Thr1558Ala." (PMID 36769678, 2023). "FDB-related hypercholesterolemia is characterized by elevated LDL cholesterol levels engendered by the reduced binding of LDL to LDL receptors and decreased clearance of apoB-containing particles by hepatocytes owing to decreased affinity between mutated APOB-100 and LDL receptors." (PMID 36499290, 2022). "To investigate the observed hypercholesterolemia, we assessed apoB secretion by 35S steady-state protein labelling in TMEM199-deficient patient-derived hepatocyte-like cells (HLCs) and found significantly increased apoB secretion (42% increase; P = .008) as compared with controls." (PMID 34626841, 2022). "Similarly, APOB, which encodes an apolipoprotein and is associated with autosomal dominant forms of hypercholesterolemia, was top-ranked by the omnibus test but not by TSS-to-top-SNP distance for disorders of lipoid metabolism in the UK Biobank." (PMID 33320851, 2020).
Hypercholesterolemia (continued). "In addition other trials such as VA-HIT and a trial conducted in hypercholesterolemia patients showed that other treatments besides statins (gemfibrozil, a fibric acid derivative, and mipomersen, an apoB inhibitor) predominantly reduced the concentration of sdLDL particles." (PMID 33166340, 2020). "ApoB-ASO-T3 conjugate may potentially be used for general obese patients with hypercholesterolemia." (PMID 28839185, 2017). "Familial hypercholesterolemia (FH; OMIM#143890) is an autosomal-dominant disease caused by a deficiency in low-density lipoprotein (LDL) receptor (ADH1) activity or in LDL-related genes (ApoB and PCSK9), which leads to obviously elevated LDL cholesterol (LDL-C) and triglyceride concentrations." (PMID 25424010, 2014). "In APOB animals, HSPB1 overexpression exerted a sex-dependent influence on obesity-related alterations, including weight gain, hypercholesterolemia, and hepatic and vWAT gene expression." (PMID 40855499, 2025). "In hypercholesterolemia and mixed hyperlipidemia, the fractions containing most of apoB and cholesterol are fractions 5–11, representing LDL, while in FDBL, cholesterol and apoB are more equally distributed between fractions 1–11, which contain IDL and LDL." (PMID 35320320, 2022). "In conclusion, this paper describes the validation of high-throughput assays to quantify the familial hypercholesterolemia biomarkers TC, LDL-C, and ApoB in DBS." (PMID 35225936, 2022). "Mipomersen, an antisense oligonucleotide against apolipoprotein B, had the potential benefit to reduce Lp(a) by 20%, but this drug is approved by the FDA only as an orphan drug for homozygous familial hypercholesterolemia." (PMID 36033567, 2022). "For example Kynamro, a second-generation 2 ́ methoxyethyl ASO targeting human apoB, has been approved by the FDA for use as an adjunct with first-line therapies to reduce apoB and total cholesterol in homozygous familial hypercholesterolemia (FH) patients." (PMID 30372444, 2018). "Since APOB mediates the binding and endocytosis of LDL by their receptors, the knockout of this gene translates into hypercholesterolemia." (PMID 25189197, 2014).
Hypercholesterolemia (continued). "Two SNALP-formulated siRNA drugs were designed to treat high levels of blood cholesterol or hypercholesterolemia, though TKM-ApoB (Tekmira) targeted ApoB; while ALN-PCS (Alnylam) targeted proprotein convertase subtilisn/kexin type 9 (PCSK9)." (PMID 23667320, 2013). "Mipomersen, an antisense oligonucleotide targeting apolipoprotein B synthesis, significantly reduces LDL-C and other atherogenic lipoproteins in familial hypercholesterolemia when added to ongoing maximally tolerated lipid-lowering therapy." (PMID 23152839, 2012). "Whereas Se supplementation upto 1 ppm leads to decreased apoB expression through increase in the LDL-R mRNA expression again via modulation of 5' -DI expression and in turn has the protective role against hypercholesterolemia." (PMID 16271152, 2005). "The drug reduces low-density lipoprotein–cholesterol (LDL-C) (20–25%), non-high-density lipoprotein–cholesterol (HDL-C) (19%), apolipoprotein B (apoB) (15%), and total cholesterol (16%) in patients with hypercholesterolemia or mixed dyslipidemia." (PMID 39598495, 2024). "The single Class 1b gene result involved the APOB gene and predicts Hypobetalipoproteinemia rather than Familial Hypercholesterolemia." (PMID 36556183, 2022). "The p.Leu167del variant is known to cause hypercholesterolemia in 3.1% of ADH subjects without LDL, APOB, and PCSK9 mutations in Spain and a French patient among a cohort of 229 ADH subjects." (PMID 35628605, 2022). "The main result of this study is that the 60-day supplementation with ALE is associated with a significant increase in HDL-C, MCP-1, and NK response and with a decrease in ApoB/ApoA and total-C/HDL-C ratio in a group of adults with low HDL-C and mild hypercholesterolemia." (PMID 30723511, 2019).